LRRC2 (leucine rich repeat containing 2)
Tractability: No criterion of Open Targets' tractability assessment is met for any kind of drug.
Gene: Protein-coding gene on chromosome 3 (46,515,385 to 46,607,097, reverse strand). Ensembl gene ENSG00000163827.
Subcellular location (Human Protein Atlas): Nucleoplasm; Cytosol; Nuclear bodies
Gene Ontology:
Biological process: intracellular signal transduction
Genetic constraint (gnomAD): Loss-of-function variants: 24 observed, 35.95 expected, observed/expected ratio (o/e) 0.67, 90% interval 0.48 to 0.94. The upper end of that interval is the gene's LOEUF score, 0.94, which puts it in group 3 of 6, group 1 being the genes least tolerant of losing a copy. Missense variants: 348 observed, 400.92 expected, observed/expected ratio (o/e) 0.87, 90% interval 0.79 to 0.95. Synonymous variants: 137 observed, 150.33 expected, observed/expected ratio (o/e) 0.91, 90% interval 0.79 to 1.05.
Homologues: Orthologues: chimpanzee LRRC2 (99% identical), macaque LRRC2 (96% identical), pig LRRC2 (90% identical), dog LRRC2 (90% identical), mouse Lrrc2 (86% identical), rabbit LRRC2 (85% identical), guinea pig LRRC2 (83% identical), rat Lrrc2 (76% identical), tropical clawed frog lrrc2 (62% identical). Paralogues in human: LRRC39 (29% identical), SCRIB (26% identical), LRRC1 (25% identical), LRRC7 (23% identical), ERBIN (22% identical), LRRIQ4 (20% identical), LRCH2 (20% identical), PHLPP2 (20% identical), LRCH1 (19% identical), LRCH3 (19% identical), LRRC28 (19% identical), LRRC8A (19% identical), and 19 more.
Diseases named in the same sentence as LRRC2 in open-access papers:
LRRC2 is named in the same sentence as 20 diseases in open-access papers, as found by Europe PMC text mining. Sharing a sentence is not in itself a finding about the gene and the disease. The quoted sentences say what the papers report.
asthma (2 papers, 2013 to 2021). "The GM13-up related to interleukin-26 (IL26, PIK3R5, and LRRC2) was much higher expressed in severe individuals while the GM12-down module related to the nervous system (10%, p = 1.77E-04, i.e., TUBB2B, SPOCK1, and ASCL1) was much lower expressed in severe asthma individuals." (PMID 34759961, 2021).
cardiac hypertrophy (2 papers, 2017 to 2020). "The other SkM or SkM/heart LRRC genes with known functionality in muscle are LRRC38, a BK channel protein, and LRRC2, a gene previously associated with heart hypertrophy and mitochondria and downregulated in SkM upon stabilized weight-loss in human SkM." (PMID 34968235, 2020). "In light of the association between compensated cardiac hypertrophy and Pgc-1α-driven mitochondrial biogenesis, it’s tempting to speculate that Lrrc2-mediated regulation of Pgc-1α could influence the hypertrophic response." (PMID 28158196, 2017). "Mechanistically, our findings are suggestive of a role for LRRC2 as a dampener of mitochondrial biogenesis and a positive regulator of cardiac hypertrophy via coordinated modulation of PGC-1α activity." (PMID 28158196, 2017).
heart failure (2 papers, 2017 to 2018). Inability of the heart to pump blood at an adequate rate to meet tissue metabolic requirements. "LRRC2 is a mitochondrial protein whose RNA expression level has been previous linked with heart failure." (PMID 29737278, 2018). "As well as being elevated in modeled hypertrophic settings, we also observed paralleled expression between LRRC2 and MYH7, an established biomarker of heart failure, in the human heart." (PMID 28158196, 2017).
autism spectrum disorder (1 paper, 2021). A spectrum of developmental disorders that includes autism, and Asperger syndrome. "A recent study showed that the expression of a LRRC2 long noncoding RNA (LCCR2-AS1) is significantly increased in children with autism spectrum disorder compared to children with normal development." (PMID 33907181, 2021).
co-infection (1 paper, 2017). "Ad-Pgc-1α alone induced ~2,000-fold increase in Pgc-1α transcript relative to Ad-GFP cells while co-infection of Ad-Pgc-1α and Ad-Lrrc2 induced a ~300-fold increase in Pgc-1a transcript." (PMID 28158196, 2017).
dilated cardiomyopathy (1 paper, 2017). Cardiomyopathy which is characterized by dilation and contractile dysfunction of the left and right ventricles. "To address a possible link to human disease, we queried LRRC2 expression in a left ventricle-derived RNASeq dataset derived from dilated cardiomyopathy (n = 140) and healthy control (n = 110) subjects and observed elevated LRRC2 transcript expression in the patient cohort." (PMID 28158196, 2017).
renal carcinoma (1 paper, 2021). A carcinoma arising from the epithelium of the renal parenchyma or the renal pelvis. "LRRC2 gene expression is impaired in renal carcinoma cell lines, this also suggesting a putative oncosuppressive gene function." (PMID 33466447, 2021).
renal cell carcinoma (1 paper, 2020). "Furthermore, its potential oncogenic role in renal cell carcinoma tumorigenesis has been confirmed, and increased levels of miR-142-3p can cause loss of function of the tumor suppressor LRRC2." (PMID 33194441, 2020).
retinal disease (1 paper, 2012). "Based on putative function and/or involvement in retinal disease, we selected 16 genes – Bach2, Cdr2, Dusp12, Esrrb, Gpsm2, Haus1, Kdm5b, Lman1, Lrp11, Lrrc2, Ncoa2, Plekha2, Ppargc1b, Trim36, Wisp1 and Zdhhc14." (PMID 22511886, 2012).
tumor (8 papers, 2016 to 2025). "Collectively, these findings suggest that LRRC2 is closely linked to tumorigenesis and may have tumor-suppressive functions." (PMID 41249120, 2025). "LRRC2 encodes a member of the leucine-rich repeat-containing family of proteins that functions in diverse biological pathways and may be a tumor suppressor." (PMID 40040643, 2024). "On the 29th day, after euthanizing the mice, the tumor weight in the Lv-LRRC2 group was found to be significantly lower than in the Lv-NC group, indicating that LRRC2 overexpression significantly inhibits tumor growth." (PMID 41249120, 2025). "In subsequent expanded in-house LUAD tumor samples (N = 41), LRRC2 expression remained significantly downregulated in tumor tissues." (PMID 41249120, 2025). "Functional experiments confirmed LRRC2 as a tumor suppressor gene, with its high expression inhibiting malignant phenotype progression." (PMID 41249120, 2025). "In the TCGA dataset, LRRC2 expression is significantly lower in LUAD tumor tissues compared to adjacent non-tumor tissues." (PMID 41249120, 2025). "Common up-regulated genes are related to transcription regulation (HMBOX1, LINC00340, NEXN-AS1), immune response (CD86, IL6, IFIT2) and the last two are potential tumor suppressors (LRRC2 and SPINK6)." (PMID 28035074, 2017). "While cg09596674 was highly methylated, LRRC2 showed lower expression in LUAD tumor tissues." (PMID 41249120, 2025). "Interestingly, some of them function as tumor suppressors (e.g. BCL2L11, MXD1, WWOX, BNIP3L, and DMTF1) or are candidate tumor suppressors having anti-proliferative properties and DNA repair abilities (e.g. LRRC2, RPA4, PPP6R1, SPEN, RAP1GAP and CISH) (see discussion section)." (PMID 26918450, 2016). "Overexpression of LRRC2 was shown to inhibit the malignant phenotype of LUAD cell lines and suppress tumor growth in vivo." (PMID 41249120, 2025). "LRRC2, a member of the leucine-rich repeat-containing (LRRC) protein family, is increasingly recognized as a potential target for tumor diagnosis and therapy." (PMID 41249120, 2025). "Regarding methylation levels, cg09596674 (LRRC2) exhibited higher methylation in both the TCGA and in-house LUAD tumor tissues compared to adjacent non-tumor tissues, while cg19220282 (SLC1A4) showed consistently lower methylation in LUAD tumor tissues." (PMID 41249120, 2025). "Differential analysis showed that methylation levels of cg09596674 were elevated in LUAD tumor tissues compared to adjacent non-tumor tissues, while LRRC2 expression was lower in tumor tissues." (PMID 41249120, 2025). "Increased LRRC2 expression inhibited LUAD cell line malignancy and suppressed tumor growth in mice." (PMID 41249120, 2025). "Additionally, LRRC2 expression in in-house LUAD tumor tissues was also lower than in adjacent non-tumor tissues." (PMID 41249120, 2025).
LRRC2 also shares sentences with these, for which no sentence is quoted: breast carcinoma (1 paper); cancer (1); cardiac disease (1); COVID-19 (1); glaucoma (1); lung adenocarcinoma (1); lung carcinoma (1); myotonic dystrophy type 1 (1); osteogenesis imperfecta (1); Treacher-Collins syndrome (1).